DKK1 (dickkopf Wnt signaling pathway inhibitor 1)
Diseases named in the same sentence as DKK1 in open-access papers (continued):
Sharing a sentence is not in itself a finding about the gene and the disease.
gastric cancer (continued). "Epigenetic regulation of DKK1 mainly occurs in the CpG island of the promoter region, and DKK1 methylation has been reported in some cancers, including gastric cancer, where its expression is silenced." (PMID 35625973, 2022). "Other evidence has shown that, by targeting DKK1, miR-501-5p can activate the Wnt/β-catenin pathway in gastric cancer cells to participate in tumor progression." (PMID 34426559, 2021). "DKK1, as an inhibitor of Wnt signaling, was also in relation to survival outcomes of gastric cancer." (PMID 34746312, 2021). "BART miRNA 10-3p has been shown to down-regulate the Dickkopf WNT Signaling Pathway Inhibitor 1 (DKK1) in EBV positive gastric carcinoma cell lines." (PMID 34234755, 2021). "DKK-1, 15 μmol/L Wnt/β-catenin signal pathway inhibitor, was added to gastric cancer cells for 48 h to detect cell proliferation and apoptosis, as well as Wnt2, p-GSK-3β, and β-catenin protein expressions." (PMID 32904598, 2020). "In this study, 15 μmol/L Wnt/β-catenin signaling pathway inhibitor, DKK-1 was added to gastric cancer cells for 48 h." (PMID 32904598, 2020). "Aberrant activation of Wnt/β-catenin signaling has been described in a variety of cancers, and inhibition of Wnt/β-catenin by DKK-1 resulted in diminution of the self-renewal capacity of a gastric cancer cell line." (PMID 30453543, 2018). "Jia reported that miR-493 mediated DKK1 down-regulation conferred proliferation, invasion and chemo-resistance in gastric cancer cells." (PMID 29137265, 2017). "Accordingly, a meta-analysis of the prognostic value of DKK1 in gastric cancer showed that DKK1 correlated with tumour invasion and poor survival." (PMID 27367730, 2016). "In conclusion, our study has revealed that miR-501-5p upregulation plays an important role in gastric cancer progression and miR-501-5p is a critical activator of Wnt/ β-catenin signaling by targeting DKK1, NKD1 and GSK3β." (PMID 27846906, 2016). "Collectively, our results suggest that miR-501-5p activates wnt/β-catenin signaling to enhance stem cell-like phenotype in gastric cancer by directly targeting DKK1, NKD1 and GSK3β." (PMID 27846906, 2016). "DKK1 is involved in three clinical trials for colorectal and gastric cancers." (PMID 39484215, 2024). "Given together, we believe that isoproterenol-mediated regulation of DKK1 by miR-493-3p may impair Wnt/-catenin pathway, resulting in the reduction of gastric cancer development, migrating, and EMT." (PMID 36762306, 2023). "The influence may be obtained by upregulating the expression of miR-493-3p, which suppressed DKK1-mediated stimulation of Wnt/β-catenin pathway and subsequently regulated gastric cancer development, and migration and EMT." (PMID 36762306, 2023). "DKK1 activates the Wnt pathway, which promotes the development of gastric cancer cells." (PMID 36762306, 2023). "Finally, these findings imply that propofol-induced miR-493-3p suppressed EMT in gastric cancer cells by inhibiting DKK1-mediated activation of Wnt/β-catenin pathway." (PMID 36762306, 2023). "However, several trials are underway to evaluate Dkk1 antibody efficacy, in several conditions such as hepatic and gastric cancers, among others." (PMID 36465166, 2022). "The aim of this study was to explore whether the ultraconserved region UC.145 regulates epigenetic changes in DKK1 expression in gastric cancer." (PMID 35625973, 2022). "Here, we developed an EMT-related RS model that was comprised of SERPINE1, PCOLCE2, MATN3, and DKK1 in gastric cancer via the LASSO method, which may classify gastric cancer patients into the high- and low-risk categories." (PMID 34746312, 2021). "DKK1 is also associated with survival outcomes in gastric cancer, with high DKK1 expression or high DKK1 expression with β-catenin positivity being an independent factor in poorer overall (OS) (P < 0.05) and disease-free survival (DFS) in gastric cancer patients." (PMID 36762306, 2023).
gastric cancer (continued). "Dickkopf-1 (DKK1) is a Wnt/ß-catenin pathway antagonist related to gastric cancer (GC) carcinogenesis." (PMID 29720122, 2018). "It has been reported that the pathway blocked by dickkopf WNT signaling pathway inhibitor 1 (DKK-1), naked cuticle homolog 1 (NKD1) and glycogen synthase kinase 3 beta (GSK3β) caused a robust reduction in the activity of wnt/β-catenin signaling and self-renewing capacity of gastric cancer cells." (PMID 27846906, 2016). "In view of the relationship between the Wnt signaling pathway and gastric cancer, we identified the prognostic five genes signatures related to the Wnt pathway in this study, including CPZ, CTHRC1, DKK1, EGF, and GPC." (PMID 40296906, 2025). "Herein, we demonstrated that miR-501-5p was substantially overexpressed in gastric cancer and induced hyper-activation of β-catenin/TCF via directly targeting DKK1, NKD1 and GSK3β." (PMID 27846906, 2016). "DKK1, a secretory antagonist that interacts with the Wnt coreceptor LRP5/6, thereby reducing cellular sensitivity to canonical Wnt ligands, has been identified as a factor that can enhance the recurrence of gastric cancer." (PMID 40296906, 2025). "Therefore, our study highlights the potential of targeted inhibition of DKK1 to reverse CDDP resistance and alleviate metastatic properties in gastric cancer." (PMID 37835450, 2023). "Moreover, high DKK1 mRNA transcripts were closely related to poor overall survival (OS) and disease-free survival (DFS) in gastric cancer, p = 0.0072 and p = 0.00042." (PMID 37835450, 2023). "Therefore, our study highlights the potential targeted inhibition of DKK1 to reverse CDDP resistance and alleviate metastatic properties in gastric cancer." (PMID 37835450, 2023). "However, the role of DKK1 in gastric cancer is not well studied or understood, especially regarding its function in gastric cancer chemoresistance." (PMID 37835450, 2023). "The authors found that miR-501-5p may directly bind and suppress several important repressors of the Wnt/beta-catenin signaling cascade [such as GSK3 beta, dickkopf-related protein 1 (DKK1) and naked cuticle 1 (NKD1)], which lead to hyperactivated signaling in gastric cancer cells." (PMID 32664914, 2020). "Furthermore, the DKK1-regulating mechanism in gastric cancer has not yet been defined." (PMID 35625973, 2022).
melanoma (36 papers, 2007 to 2025). A malignant, usually aggressive tumor composed of atypical, neoplastic melanocytes. "In addition, increased Wnt5a expression levels in melanoma tissues as well as diminished levels of the soluble Wnt antagonist, Dkk-1, have been associated with an inferior clinical outcome in patients with advanced melanoma." (PMID 25339948, 2014). "In light of our findings, a further clinical study is necessary to clarify whether DKK1 could be utilized as a diagnostic serum biomarker for melanoma patients." (PMID 24733089, 2014). "Our lab and others have also demonstrated that DKK1 drives the accumulation of suppressive myeloid populations in melanoma, lung carcinoma, prostate, and gastric cancer, ultimately reducing T cell and NK cell responses." (PMID 39885132, 2025). "Despite the low secretion of DKK1, tumor growth of MDA-MB435 melanoma cells was suppressed through the activation of cell death; this also reflects the inhibitory role of DKK1 in tumorigenicity." (PMID 35355709, 2022). "DKK1 was found to be repressed by G9a overexpression in immortalized primary melanocytes, as well as upregulated when G9a was knocked down in melanoma cells." (PMID 34691767, 2021). "DKK1, in turn, is a secreted inhibitor of Wnt signaling, and its overexpression decreases the invasive capability of melanoma cells in vitro and increases apoptosis in melanoma cells in vitro and in vivo." (PMID 32053263, 2020). "When melanoma cell lines were directly treated with recombinant human DKK1 proteins, melanin production was robustly suppressed." (PMID 29271951, 2017). "Our recent study showed that NSC-CM increased depigmentation via the inhibition of Wnt/β-catenin signaling pathway by triggering DKK1 upregulation in a melanoma cell line and subsequent downregulation of the expression of MITF and melanogenic enzymes." (PMID 29271951, 2017). "It has been demonstrated that DKK1 expression is reduced in melanoma cells compared with melanocytes, but its role in melanomagenesis is not well recognized." (PMID 27351373, 2016). "It significantly reduced the transcript levels of LEF1, WNT10B, MITF-M, c-MYC and CCND1 and increased the mRNA levels of FZD7 and DKK1 in all melanoma cell populations." (PMID 27351373, 2016). "For instance, the expression of CTGF was selectively reduced by pentoxifylline in CTGFhigh/β-cateninhigh populations, DMBC17 and DMBC21 in contrast to expression of DKK1, which was increased in all melanoma cell populations." (PMID 27351373, 2016). "More recently, a prospective pilot study revealed that the DKK1 serum levels of melanoma patients were significantly higher than in healthy controls." (PMID 24733089, 2014). "We constructed stable DKK1 and DKK2 B16F10 melanoma cell lines by transfection with lenti-viral vectors (Lenti-DKK1 and Lenti-DKK2)." (PMID 24091497, 2014). "Treatment of B16F10 melanoma-bearing mice with adenovirus expressing DKK1 significantly reduced tumor growth but DKK2 increased growth compared with controls." (PMID 24091497, 2014). "The expression levels of DKK-1 are also reportedly downregulated in melanoma cells and colorectal cancer." (PMID 25144498, 2014). "We injected B16F10 melanoma cells into DKK1 Tg and DKK2 Tg mice, and their wild-type littermates, and evaluated tumor growth and angiogenesis." (PMID 24091497, 2014). "Nonetheless, a reduction in DKK1 expression was observed in melanoma cell lines compared to melanocytes." (PMID 24733089, 2014). "Consistently, melanoma blood vessels in DKK1 Tg mouse tumor sections stained less for beta-catenin (37 % reduction) compared with that in control mice." (PMID 24091497, 2014). "DKK1 is an extracellular inhibitor of anti-apoptotic Wnt-signaling pathway that can induce apoptosis in melanoma cells." (PMID 23028975, 2012). "In twenty melanoma metastasis tissue samples average DKK1 mRNA level was shown to be significantly (p<0.05) lower in high CT16 expressing tumors (n = 3) when compared to the tumors with low CT16 expression (n = 17)." (PMID 23028975, 2012).
melanoma (continued). "Most interestingly, CT16 was found to be a negative regulator of DKK1, a gene described to be significantly downregulated in malignant melanoma." (PMID 23028975, 2012). "The extracellular Wnt antagonist DKK1 was chosen for further studies, since it has previously been shown to activate apoptosis and to be downregulated in melanoma and other cancers." (PMID 23028975, 2012). "Thus, DKK1 targeting has been successfully used in combination with ICB in mouse models of melanoma and gastric cancer." (PMID 39885132, 2025). "In addition, DKK1 activation in melanoma gives rise to apoptosis in vivo, and DKK1 also plays a suppressor role in melanoma." (PMID 37835450, 2023). "The many roles of G9a, from the repression of stem cell factors in early development and CD4 during CD8+ T cell differentiation to inhibiting the DKK1 repression of Wnt signal in melanoma, highlight the broad range of functions that are controlled by the epigenetic regulation of histone methylation." (PMID 34691767, 2021). "DKK1 inhibits tumor growth by activating apoptosis of MDA-MB435 melanoma cells." (PMID 24091497, 2014). "DKK1 is epigenetically silenced in several cancers such as human melanoma and renal cell carcinoma." (PMID 24091497, 2014). "In our study, the high monolayer expression of DKK1 was accompanied by increased invasiveness, indicating that the suppression of the Wnt pathway might increase the invasive potential of melanoma cells." (PMID 24733089, 2014). "Furthermore, the silencing of DKK1 in monolayers increased the percentage of clonogenic cells, suggesting a role for Wnt signaling in promoting melanoma cell self-renewal." (PMID 24733089, 2014). "Forced expression of DKK1 or WIF-1 reduces melanoma cell growth and activates cell death." (PMID 24416617, 2013). "We also suggest that human melanoma skin metastasis samples with high CT16 mRNA level may have less DKK1 mRNA than those with low CT16 mRNA level." (PMID 23028975, 2012). "Therefore, decrease in DKK1 expression is considered to be an important survival mechanism in melanoma cells." (PMID 23028975, 2012). "Surprisingly, DKK1 was barely detected in two other melanoma lines that were positive for mRNA." (PMID 17245340, 2007). "Although it has been suggested that DKK1 could be a novel diagnostic/prognostic serum biomarker for a wide range of human cancers, serological samples from melanoma patients were not included in that study." (PMID 24733089, 2014). "Expression of Tnf, Il1b, Pros1, and Gas6 was enhanced upon tumor growth in vivo, as was Dkk1, in contrast to studies showing down-regulation of DKK genes in melanoma cell lines in vitro, relative to melanocytes." (PMID 37043573, 2023). "In a significant proportion of melanomas, WFDC1 is downregulated by hypermethylation and has been shown to inhibit expression of DKK1, a known WNT signaling inhibitor." (PMID 35269844, 2022). "DKK1, DKK2 and DKK3 downregulation has been observed in melanoma cell lines and tissue samples, however, in contrast to other cancer types promoter hypermethylation is responsible only for downregulation of DKK2." (PMID 32659938, 2020). "Meanwhile, HLA-DRA, INHBA, DKK1, CTGF, PMP22, FLRT3 and NRCAM genes, upregulated in G10, were described as overexpressed in invasive melanomas." (PMID 27206673, 2016). "Our findings show that DKK1 inhibits vessel perfusion and reduces perivascular coverage in B16F10 melanoma tumors." (PMID 24091497, 2014). "Collectively, these results suggest that the effects of DKK1 and DKK2 on B16F10 melanoma growth are mainly exerted through regulating angiogenesis with no direct action on tumor cell proliferation." (PMID 24091497, 2014). "This study examined the effects of DKK1 and DKK2, known Wnt antagonists, on B16F10 melanoma tumor proliferation and angiogenesis by using viral-mediated tumor transfectants and transgenic mice." (PMID 24091497, 2014). "To assess this possibility, we evaluated DKK1 and DKK2 effects on B16F10 melanoma cellular function." (PMID 24091497, 2014).
melanoma (continued). "Ectopic DKK1 expression suppressed tumor growth by inducing apoptosis and inhibiting proliferation in both renal cell carcinoma and MDA-MB-435 melanoma." (PMID 24091497, 2014). "To study the effect of DKK1 and DKK2 on tumor angiogenesis and proliferation, we injected either adenoviral-mDKK1 (Ad-DKK1) or -mDKK2 (Ad-DKK2) constructs into B16F10 melanomas that had been established in syngeneic C57BL/6 mice." (PMID 24091497, 2014). "In the present study, we investigated the effects of DKK1 and DKK2 in tumor growth and angiogenesis in a murine model of B16F10 melanoma." (PMID 24091497, 2014). "When we analyzed 20 melanoma skin metastases in their DKK1 and CT16 mRNA expression, three samples showed exceptionally high CT16 levels and concomitantly very low DKK1 expression." (PMID 23028975, 2012). "The suppression of DKK1 activates WNT signaling, fostering melanoma cell growth." (PMID 40554927, 2025). "According to D’Amico, DKK1 activates Myeloid-derived suppressor cell (MDSC), a suppressor of tumor immunology, to indirectly reduce accumulation of CD4+ and CD8+ TILs in Lewis lung carcinoma, pancreatic cancer as well as B16 melanoma." (PMID 31830954, 2019). "DKK1 and DKK2 were undetectable in B16F10 melanoma cells, whereas DKK3 and DKK4 were expressed." (PMID 24091497, 2014). "Neither DKK1 nor DKK2 stable melanoma cell line proliferation was significantly different compared to the Lenti-GFP cell line." (PMID 24091497, 2014). "Additionally, expression of negative regulators of canonical Wnt signaling pathway such as Dickkopf-1, 2, 3 (Dkk-1, 2, 3) and Wnt inhibitory factor-1 (WIF-1) is strongly reduced or lost, both in melanoma cell lines and tumor samples." (PMID 24416617, 2013). "We further evaluated DKK1 in cell extracts from these two melanoma lines, but no protein was detected, excluding the possibility that DKK1 is sequestered inside the cell (data not shown)." (PMID 17245340, 2007). "Neither DKK1 nor DKK2 affect B16F10 melanoma cell proliferation and survival." (PMID 24091497, 2014). "Thus, DKK1 and MITF might be considered as important regulators of microenvironment-driven alterations of melanoma phenotype." (PMID 24733089, 2014). "Thus, our data suggest that CT16 overexpression is one, but probably not the only mechanism that leads to DKK1 suppression in melanoma." (PMID 23028975, 2012). "Unlike Ad-DKK1, Ad-DKK2 infection increased B16F10 melanoma vessel density to levels 171 % of Ad-Mock controls." (PMID 24091497, 2014). "However, we found that both DKK1 and DKK2 did not modulate tumor cell proliferation in stably-transfected melanoma cells." (PMID 24091497, 2014).